RHOA (ras homolog family member A)
Diseases named in the same sentence as RHOA in open-access papers (continued):
Sharing a sentence is not in itself a finding about the gene and the disease.
tumor (continued). "Because RhoA/ROCK1 signaling is also closely related to tumor EMT and metastasis, we further investigated the role of HIF‐1α in DDR1‐induced EMT and metastasis in GC." (PMID 39024501, 2024). "We found that also in the case of SCC, the opposite targeting of p110δ PI3K in macrophages and RhoA in tumour cells abrogated A431 SCC tumour growth and metastasis as it was suggested by the abolishment of the tumour cell blood burden." (PMID 38182748, 2024). "Mechanistically, macrophage-tumor cell contact activates RhoA signaling in tumor cells, which initiates invadopodium formation in the tumor cell." (PMID 39555068, 2024). "These intracellular bacteria inhibit RhoA/ROCK-induced contractility of tumor cells while being exposed to FSS, conferring protection against mechanical-force-induced apoptosis of tumor cells during metastasis." (PMID 39272898, 2024). "We further reveal the role of H2O2 gradient to induce chemotaxis of tumor cells by activating Src and subsequently inhibiting RhoA." (PMID 38279020, 2024). "Our data show that the efficiency of this combined treatment is associated with decreased ATX expression in tumour cells and tumour stroma and emerge a reverse link between ATX and RhoA." (PMID 38182748, 2024). "Sema3F is a potent inhibitor of tumor angiogenesis and metastasis where it inactivates RhoA, depolymerizes F-actin, and suppresses tumor cell migration." (PMID 38592275, 2024). "We then assessed the impact of the combined opposite targeting of p110δ PI3K and RhoA on cancer cells metastasis by determining the tumour cell blood burden and the expression of vimentin in the lungs." (PMID 38182748, 2024). "The reduced ATX expression upon increased RhoA activity into tumours and on the other hand the induced RhoA expression and activity upon inhibition of ATX activity in cancer cells emerges a negative reverse link between RhoA and ATX." (PMID 38182748, 2024). "Rho GTPases, a kind of regulator for intracellular actin dynamics, mainly consisting of RhoA, Rock1/2, Cdc42, and Rac1, can dramatically interfere with the motility of tumor cells." (PMID 36969843, 2023). "Nuclear p120-catenin controls the anchorage-independent upregulation of Wnt11 by repressing Kaiso-mediated transcription, thereby promoting RhoA activation.α-catenin inhibits tumor progression, and is downregulated in BC with a more metastatic phenotype." (PMID 37537585, 2023). "Although the sample size was small, they found that RHOA mutations were predictive of a favourable outcome, potentially due to tumour suppressor functions for RHOA; although, this remains to be determined." (PMID 36836878, 2023). "This action leads to increased monolayer permeability due to increased activity of RhoA, expression of F-actin, and reduced expression of Z0-1, promoting tumor metastasis." (PMID 37189687, 2023). "A synergistic effect between TET2 and RHOA G17V in inducing tumor cell proliferation was discovered in mouse models of AITL with TET2 deletion and RHOA G17V mutation." (PMID 37188182, 2023). "ROCK1 serves an important function in cell migration and invasion in neoplasms, and is the classic downstream effector of the small GTPase RhoA, the activation of which is mediated by AKT phosphorylation." (PMID 37369706, 2023). "That is, a low level of p-MYPT1 can decrease the expression of RhoA, thus inhibiting the migration and invasion of tumor cells." (PMID 37446748, 2023). "The ectopic expression of PLCD1 decreases tumor cell motility by modulating cytoskeletal recombinant proteins, including RhoA and phospho-cofilin." (PMID 37685980, 2023). "RhoA is highly expressed in breast malignancies and is closely related to tumor cell proliferation, invasion and metastasis." (PMID 36882618, 2023).
tumor (continued). "By transfecting active RhoA (Q63L) (CA-RhoA) into tumor cells, we found that YAP phosphorylation was inhibited in soft fibrin gels." (PMID 37614365, 2023). "RHOA mutations encoding a Gly17Val alteration affecting GTPase activity and inhibiting the proposed tumor suppressor function of active RHOA was identified in 53-68% of AITL cases and was similarly identified to coexist with the presence of a TET2 mutation." (PMID 36776886, 2023). "Autophagy serves as a RhoA regulator, which aids in maintaining an appropriate amount of active RhoA in cells in order to prevent tumor metastasis." (PMID 37298689, 2023). "TRPV4 can affect tumor angiogenesis and inflammatory microenvironment, intervene in the cytoskeleton-related proteins including RhoA, CDC42, and Rac1, and promote cancer cells EMT." (PMID 37369706, 2023). "uPAR expression, in fact, is increased in EC with Marimastat as well as Ephrin A1 expression, that it is known to promote RhoA activation and amoeboid transition in tumor cells." (PMID 36759828, 2023). "Like SDC4, the CD44 cytoplasmic domain is reported to mediate cell migration through Rac1 and RhoA in human tumor cell lines." (PMID 36735684, 2023). "The MET signaling pathway is also involved in the motility of tumor cells and is particularly important for acquiring an invasive property via RhoA and Src." (PMID 37547755, 2023). "Recent studies have revealed that RhoJ blockade destroys tumor blood vessels by activating the RhoA- ROCK signaling pathway in various tumor models." (PMID 35173528, 2022). "ARHGAP25 positivity rates in NSCLC and paracancerous tumor-free tissues were 48.5% and 63.1%, respectively, whereas RhoA positivity rates were 62.3% and 18.5%, respectively." (PMID 36207695, 2022). "Further mechanistic detection revealed that miR-210 negatively regulated EFNA3 expression and participated in the PI3K/AKT/VEGFA or Wnt/Β-catenin/RHOA pathways, thus promoting tumor angiogenesis and cellular permeability." (PMID 36466111, 2022). "RhoA is highly expressed in a range of tumor tissues, closely correlated with tumor malignancy, and plays an invaluable role in neoplastic metastasis and development." (PMID 36207695, 2022). "Both HNRNPC and RhoA mRNA expression levels were significantly higher in PC patient tumour samples than the corresponding adjacent non‐tumour tissue." (PMID 35277915, 2022). "The overexpression of RhoA and RhoC can disrupt cell-cell junctions and induce the migration of tumor cells promoting the adhesions between cells and the extracellular matrix." (PMID 35793608, 2022). "RhoA potentiates the outgrowth of disseminated tumor cells on osimertinib treatment, preferentially in response to extracellular laminin and in the brain." (PMID 36509758, 2022). "PRUNE2 is a tumor suppressor in prostate and other cancers, inhibiting Ras homolog family member A (RhoA) activity to support oncogenic transformation." (PMID 36970726, 2022). "Both Rho GTPase-activating protein 25 (ARHGAP25) and Ras homolog family member A (RhoA) are effective predictors of tumor metastasis." (PMID 36207695, 2022). "Focally deleted regions identified the tumour-suppressor genes RHOA at 3p21, CDKN2A and CDKN2B at 9p21, RAD51B, MAX, DICER1, BCL11B, NKX2-1, CCNB1IP1 and BAZ1A at 9q33." (PMID 34980126, 2022). "Steroidogenic acute regulatory protein-related lipid transfer domain-containing protein 13 (StarD13) is a GAP for RhoA and Cdc42 with potential tumor suppressor functions." (PMID 34958986, 2022). "We found that HNRNPC and RhoA mRNA and protein expression levels were significantly higher in PC tissues compared to adjacent non‐tumour tissue." (PMID 35277915, 2022). "In both cases, RHOA expression was required for tumor development and survival in both in vitro and in vivo." (PMID 35371049, 2022). "The ARHGEF18 (Rho/Rac Guanine Nucleotide Exchange Factor 18), also known as P114-RhoGEF, activates the downstream gene RhoA, which is important for cell migration and tumor progression." (PMID 36552904, 2022).
tumor (continued). "Chemokines and cytokines regulate the activation of RhoA to initiate the cytoskeletal changes required for the physical movement of the cells into the tumor stroma." (PMID 35811723, 2022). "As an IHC marker, RhoA showed less staining variation between tumour cells than did D2-40 in epithelioid MM." (PMID 36323745, 2022). "As an important chemokine receptor, CXCR4 is reported that it can regulate tumor cell migration, invasion, and cytoskeleton rearrangements through activating RhoA." (PMID 36552718, 2022). "Here, we showed that NPFFR2 is overexpressed in HCC and associated with a poor prognosis and identified that NPFFR2 is critical for tumor cell survival and aggressiveness, and these functions in cancer depend on RhoA and its downstream signaling YAP pathway." (PMID 36497331, 2022). "Tumor capillary endothelial cells (ECs) show abnormally high levels of RHOA, resulting in aberrant mechanosensing and excessive angiogenesis." (PMID 36348464, 2022). "Cyclin D1 enhances cell migration and invasion activity in fibroblasts by regulating RhoA as well as tumor cells." (PMID 35945910, 2022). "The present study examined radiation‐resistant PC tissue samples from clinical patients for both HNRNPC and RhoA levels, which are involved in the proliferation and migration of tumour cells." (PMID 35277915, 2022). "IHC staining revealed that HNRNPC and RhoA protein expression levels were also significantly increased in the PC patient tumour samples compared to the adjacent normal tissue." (PMID 35277915, 2022). "Hypoxia-derived exosomal circ-133 is transferred into normoxic CRC cells and promotes CRC cell migration through the miR-133a/GEF-H1/RhoA axis; this finding reveals a potential mechanism by which intra-tumor oxygen heterogeneity promotes tumor progression." (PMID 35382838, 2022). "It was found that increasing tumor cell proliferation and invasive capacity by inhibiting RhoA‐ROCK axis." (PMID 35373928, 2022). "The present study results have shown that BVES co-localized with ZO-1 and GEFT to regulate tumor cell extrusion by reducing RhoA protein activity, thus inhibiting myosin contraction." (PMID 36123685, 2022). "In this study, we conducted Sanger sequencing of formalin-fixed paraffin-embedded (FFPE) diagnostic tumor samples using a target-panel to search for recurrent mutations involving the IDH-1/IDH-2, TET-2, DNMT3A and RhoA genes in 59 cases of nMTCL." (PMID 36536430, 2022). "Tumor-bearing nude mice were additionally used to assess the relationship between lentivirus-mediated alterations in RhoA expression and MPPa-PDT treatment outcomes." (PMID 34627383, 2021). "CTNNB2(β-catenin) and RHOA in Wnt/β-catenin were related to focal adhesion and regulated tumor metastasis and invasion." (PMID 34486492, 2021). "Although Rho GTPases, such as RhoA, RhoB, RhoC, and RhoE, promote tumor metastasis, the main roles of Rho GTPases remain unidentified." (PMID 33406809, 2021). "Levobupivacaine and ropivacaine reduced tumor cell invasion and migration by reducing RhoA protein levels." (PMID 34950031, 2021). "Upon activation, RhoA modulated cytoskeletal contractility through F-actin and actomyosin, enhancing the intrinsic ability of tumour cells to survive haemodynamic forces, favouring metastasis." (PMID 34241735, 2021). "In the context of chronic lymphocytic leukemia, CDC42 upregulation, together with downregulation of RAC1 and RHOA, upon direct contact with tumor cells, impairs migration of T cells and therefore immunosurveillance." (PMID 33406731, 2021). "When tumour cells transited zebrafish and mouse microvasculature, RhoA-ROCK dependent actin filament polymerization induced a change of the CTCs shape from elongated to spherical, promoting a stable arrest, cell survival and enhanced extravasation of CTCs." (PMID 34241735, 2021). "Specifically, HGF/Met induces the proliferation and migration of endothelial and tumour cells through RhoA, Rac1, and Cdc42 activation." (PMID 34202487, 2021).
tumor (continued). "c-Myc promotes RhoA mRNA expression, thereby enhancing the migration and invasion ability of tumor cells." (PMID 33858415, 2021). "The allosterisms of actin and myosin in ECM promote structural remodeling and tumor cell polarization during tumor cell migration; Ras homolog gene family, member A (RhoA), MMP, and non‐muscle Myosin‐II are involved in the allosterisms of these two proteins." (PMID 34977870, 2021). "The imbalance between GTP and GDP, in turn, activates GTPase proteins such as RhoA, which then stimulates tumor proliferation and progression." (PMID 34830698, 2021). "In early studies, RhoA GTPases were reported to be overexpressed in cancers and suggested an oncogenic role in tumor progression." (PMID 34465801, 2021). "In one study, tumour cells acquired the ability to withstand subsequent FSS damage by RhoA activation." (PMID 34241735, 2021). "Priming with CpG attenuated Il6 and Nlrp3 expression, further upregulated expression of Nod2, Oas2, RhoA, Pycard, Tlr1/2 and Il12, and enhanced T-cell number and activation while polarizing macrophages to an anti-tumor phenotype." (PMID 33441763, 2021). "MITF contributed to cell proliferation, migration, invasion and tumor growth in ccRCC through activation of the RhoA/YAP signaling pathways." (PMID 34208068, 2021). "These exosomes promoted the invasion and metastasis of tumor cells by acting on the miR-133a/GEF-H1/RhoA signaling pathway in tumor cells derived from normal partial pressure of oxygen." (PMID 35003365, 2021). "ROCK1, as an effector of the small GTPase RhoA, is usually upregulated in different cancers and can increase cancer cell motility to promote tumor invasion and metastasis." (PMID 34271873, 2021). "At the immune system level, it promotes infiltration of M1-like macrophages and inhibits tumor metastasis by activating the SPON2-α5β1 integrin signaling that in turn inactivates RhoA and prevents F-actin assembly." (PMID 34445986, 2021). "ULK1/2 has been linked to diverse oncogenic or tumor-suppressive signalling cascades (e.g., KRASG12D/Copper, PI3K/AKT/mTOR, FAK/RhoA, STK11/liver kinase-B1 [LKB1]) that are engaged in pathogenesis of solid tumors from various types 50-52." (PMID 34345207, 2021). "A recent report demonstrated that IGF-1–stimulated F-actin reorganization and cell motility occurs via the upregulation of RhoA protein expression and activity through the mTOR signaling pathway in tumor cells." (PMID 34627341, 2021). "As it is known that PTMs of RhoA are essential for its function, the inhibition of different steps of these modifications has been analyzed with regard to effects on RhoA function in tumor cells and cardiomyocytes." (PMID 33906663, 2021). "It is of great significance to develop drugs targeting ERK, c-Myc and RhoA for the treatment and prevention of tumor metastasis." (PMID 33858415, 2021). "A study in 2014 showed that the activation of Wnt/β-catenin signaling through RHOA inactivation can accelerate tumor development." (PMID 33406731, 2021). "RhoA overexpression was observed in advanced histologic grade, larger tumor size, and stages II-III of BrCa." (PMID 33407452, 2021). "Previous studies have found that p27 acts as a tumor suppressor by closely binding to CIT to prevent its interaction with its activator RhoA, thereby regulating cytokinesis." (PMID 34305997, 2021). "Recent studies have shown that TYRO3 is activated by extracellular vesicles whereupon it can promote invasive tumor cell metastasis and chemoresistance by activating RhoA or YAP." (PMID 34627383, 2021). "ARHGAP5 (p190RhoGAP) is frequently deleted in oligodendrogliomas, and its overexpression inhibits glial proliferation and tumor formation by downregulating RhoA activity." (PMID 32392742, 2020). "This was consistent with the antagonistic relationship between RhoA and Rac1 observed in other tumor types." (PMID 32900380, 2020).
tumor (continued). "Studies have found that RhoA is overexpressed in a variety of cancer tissues and cancer cells and is closely related to tumor invasion and metastasis." (PMID 33336057, 2020). "Mokady and Meiri also showed that RhoA is overexpressed in many solid tumors, whereas RhoB acted more as a tumor suppressor with pro-apoptotic effects." (PMID 33162807, 2020). "Neddylated Smurfs modulate cellular processes in tumors, as shown in colorectal cancer, including cell proliferation, growth, invasion, and migration, by degrading tumor suppressors (e.g., RhoA), ultimately promoting cancer progression." (PMID 33718111, 2020). "A number of studies have demonstrated the anti-tumor activity of statins via a variety of mechanisms, including inhibition of RhoA, NF-κB, Arf6 or PI3K signaling." (PMID 32541798, 2020). "In particular, the physical heterotypic contact between macrophages and breast cancer cells activates the RhoA pathway, resulting in increased invadopodium formation in tumor cells at blood vessels." (PMID 33178698, 2020). "For example, the RhoA/ROCK signaling pathway has been found to participate in IL-6-mediated tumor invasion and distant metastasis." (PMID 33158289, 2020). "COX-2 stimulates the RhoA/Rho kinase pathway, which leads to disruption of tumor cell adherens junction formation and contributes to tumor progression." (PMID 33537234, 2020). "RhoA, Rac1 and Ras are members of Ras super family of small GTPases that are critically involved in tumor cell biological activities such as migration, growth and survival." (PMID 32085741, 2020). "Although controversial, the roles of RhoA GTPase and actin SF in tumor growth and metastasis have been extensively studied." (PMID 33158289, 2020). "We found that endogenously synthesized FN in adherent tumor cells was required for periFN assembly which was aligned by RhoA-organized actin stress fiber (SF)." (PMID 33158289, 2020). "Archived tumor samples from 106 women from three different cohorts showed that RhoA and RhoB were both more highly expressed in luminal tumors than in triple negative tumors." (PMID 33162807, 2020). "CCNA2 participates in the modulation of RhoA activity and its dysregulation by autophagy in the late phase of mitosis appears to be associated with EMT, affecting the aggressiveness of the tumor." (PMID 33665162, 2020). "In congruence with the pro-metastatic property of periFN, RhoA, and actin SF, despite their tumor suppressive roles in the early tumor development, have been shown to endow tumor cells with metastatic-promoting activities in late stages of tumor progression." (PMID 33158289, 2020). "Although the tumor type was different from those examined in past studies, in our study, RhoA expression was higher in patients with more advanced stage disease and in those with metastasis." (PMID 31976530, 2020). "Altogether, these findings lead to a possibility that periFN assembly on tumor cells is organized and aligned by SF cytoskeleton that is regulated by activated RhoA." (PMID 33158289, 2020). "The Ras homolog family member A/Rho-associated protein kinase 1 (RHOA/ROCK) and TGF-β pathways also induce the invasion and migration of tumor cells, and are associated with lymph node damage and EMT activation." (PMID 33142817, 2020). "In this study, we have determined that the shutdown of existing tumor vessels by TS-PDT involves the RhoA/ROCK pathway." (PMID 32825648, 2020). "Rac1 and RhoA regulation of focal complexes assembly and maturation into focal adhesions is required for the effective cell migration of different tumor models." (PMID 32900380, 2020). "In the literature, overexpression of RhoA has been found in different tumors compared to normal tissue, often correlated with tumor aggressiveness." (PMID 33162807, 2020). "These functions of RhoA and Rac1 become crucial for angiogenesis and tumour initiation, invasion and metastasis." (PMID 32731493, 2020).